HGSNAT (heparan-alpha-glucosaminide N-acetyltransferase)
Description:
Lysosomal acetyltransferase that acetylates the non-reducing terminal alpha-glucosamine residue of intralysosomal heparin or heparan sulfate, converting it into a substrate for luminal alpha-N-acetyl glucosaminidase.
Synonyms: TMEM76; FLJ32731; HGNAT; MPS3C; RP73
Tractability: Small molecule: a structure with a bound ligand is known. Antibody: its Gene Ontology location is reachable by antibodies, with high confidence; UniProt predicts a signal peptide or a membrane-spanning region. PROTAC: ubiquitination databases record sites on it; its protein half-life has been measured.
Gene: Protein-coding gene on chromosome 8 (43,140,376 to 43,202,855, forward strand). Ensembl gene ENSG00000165102.
Subcellular location: Lysosome membrane
Pathways (Reactome):
Disease: MPS IIIC - Sanfilippo syndrome C
Immune System: Neutrophil degranulation
Metabolism: HS-GAG degradation
Gene Ontology:
Molecular function: acyltransferase activity; heparan-alpha-glucosaminide N-acetyltransferase activity
Biological process: lysosomal transport; protein complex oligomerization; heparan sulfate proteoglycan catabolic process
Cellular component: lysosomal membrane; plasma membrane; specific granule membrane; tertiary granule membrane; lysosomal lumen
Genetic constraint (gnomAD): Loss-of-function variants: 37 observed, 48.7 expected, observed/expected ratio (o/e) 0.76, 90% interval 0.58 to 1. The upper end of that interval is the gene's LOEUF score, 1, which puts it in group 4 of 6, group 1 being the genes least tolerant of losing a copy. Missense variants: 537 observed, 593.41 expected, observed/expected ratio (o/e) 0.9, 90% interval 0.84 to 0.97. Synonymous variants: 240 observed, 245 expected, observed/expected ratio (o/e) 0.98, 90% interval 0.88 to 1.09.
Gene-disease validity (ClinGen):
ClinGen rates the evidence that HGSNAT causes each of these diseases.
inherited retinal dystrophy (autosomal recessive): Definitive. An instance of retinal degeneration that is caused by an inherited modification of the individual's genome.
mucopolysaccharidosis type 3C (autosomal recessive): Definitive. A rare autosomal recessive lysosomal storage disease caused by deficiency of the enzyme acetyl-CoA:alpha-glucosaminide acetyltransferase.
Homologues: Orthologues: chimpanzee HGSNAT (100% identical), macaque HGSNAT (97% identical), dog HGSNAT (85% identical), rat Hgsnat (83% identical), mouse Hgsnat (81% identical), rabbit HGSNAT (73% identical), tropical clawed frog hgsnat (55% identical), zebrafish hgsnat (53% identical), Drosophila melanogaster Hgsnat (33% identical), guinea pig Hgsnat (16% identical).
Diseases named in the same sentence as HGSNAT in open-access papers:
HGSNAT is named in the same sentence as 35 diseases in open-access papers, as found by Europe PMC text mining. Sharing a sentence is not in itself a finding about the gene and the disease. The quoted sentences say what the papers report.
lysosomal storage disorder (11 papers, 2016 to 2025). "Sanfilippo syndrome C, an inherited metabolic disorder, is a rare lysosomal storage disorder caused by mutations in the heparan--glucosaminide N-acetyltransferase HGSNAT gene, which results in heparan sulphate buildup." (PMID 39767643, 2024). "Mutation-induced dysfunction in HGSNAT causes abnormal accumulation of HS within the lysosomes and leads to an autosomal recessive neurodegenerative lysosomal storage disorder called mucopolysaccharidosis IIIC (MPS IIIC)." (PMID 37961489, 2024). "Mucopolysaccharidosis III type C (MPS IIIC) is an untreatable neuropathic lysosomal storage disease caused by a genetic deficiency of the lysosomal N-acetyltransferase, HGSNAT, catalyzing a transmembrane acetylation of heparan sulfate." (PMID 38786099, 2024). "Mutations in HGSNAT usually cause Sanfilippo Syndrome/Mucopolysaccharidosis Type IIIC—a severe multisystemic lysosomal storage disease that presents in infancy or childhood and leads to mental retardation, early death and, among other problems, RP." (PMID 28981474, 2017). "Mucopolysaccharidosis type IIIC (MPSIIIC) is a severe lysosomal storage disease caused by deficiency in activity of the transmembrane enzyme heparan-α-glucosaminide N-acetyltransferase (HGSNAT) that catalyses the N-acetylation of α-glucosamine residues of heparan sulfate." (PMID 27491071, 2016). "HGSNAT is a critical lysosomal membrane enzyme involved in the devastating lysosomal storage disease Sanfilippo syndrome." (PMID 38918376, 2024). "MPS III is an autosomal recessive lysosomal storage disease caused mainly by missense variants in the NAGLU, GNS, HGSNAT, and SGSH genes." (PMID 38802532, 2024). "Mutations of HGSNAT cause HS accumulation and consequently mucopolysaccharidosis IIIC, a devastating lysosomal storage disease characterized by progressive neurological deterioration and early death where no treatment is available." (PMID 38918376, 2024). "Unlike other lysosomal storage disorders, the absence of HGSNAT did not affect the morphology of interstitial macrophages." (PMID 37756356, 2023).
Mucopolysaccharidosis type IIIC (11 papers, 2014 to 2025). "Mutations in the HGSNAT gene cause mucopolysaccharidoses III type or Sanfilippo syndrome type C due to a deficiency of acetyl-CoA a-glucosaminide N-acetyltransferase (EC 2.3.1.78) that catalyzes the degradation of heparan N-sulfatase (sulfamidase)." (PMID 38248833, 2023). "Sanfilippo syndrome type C is caused by a deficiency in an enzyme located in the lysosomal membrane, heparan-alpha-glucosaminide N-acetyltransferase (HGSNAT, EC 2.3.1.78), which is encoded by the HGSNAT gene." (PMID 32121121, 2020). "We have differentiated iNs and iAs from three different previously generated iPSC lines carrying mutations in the HGSNAT gene, responsible for Sanfilippo C syndrome." (PMID 32121121, 2020). "In that report, USH2A gene defects were identified in 14.3% of solved cases, whereas mutations in the HGSNAT gene (typically responsible for Mucopolysaccharidosis type IIIC) were a relatively common cause of pericentral RP." (PMID 31877679, 2019). "HGSNAT mutations most commonly cause Mucopolysaccharidosis type IIIC, but review of the literature reveals nonsyndromic RP cases with what is essentially a pericentral phenotype (see Discussion)." (PMID 28981474, 2017). "Sanfilippo syndrome type C (MPS IIIC) is caused by mutations in the HGSNAT gene." (PMID 25491247, 2014). "For Sanfilippo syndrome type C, we carried out a preclinical cell-based study showing a 2.5-fold increase of HGSNAT enzyme activity using glucosamine in patients’ fibroblasts carrying one splicing mutation that produces a protein lacking four amino acids." (PMID 33105639, 2020). "In the case of Sanfilippo syndrome type C, glucosamine, a competitive HGSNAT inhibitor, has been shown to increase residual enzyme activity in cultured skin fibroblasts from patients affected with a number of missense mutations." (PMID 25491247, 2014). "Mucopolysaccharidosis type IIIC is a neurodegenerative lysosomal storage disorder (LSD) characterized by the accumulation of undegraded heparan sulfate (HS) due to the lack of an enzyme responsible for its degradation: acetyl-CoA:α-glucosaminide N-acetyltransferase (HGSNAT)." (PMID 39941041, 2025). "Considering that HGSNAT is a lysosomal transmembrane protein that does not shuttle through the 6-mannose phosphate pathway, Sanfilippo C syndrome might not be the best candidate for this therapeutic strategy." (PMID 32121121, 2020).
Sanfilippo Syndrome (7 papers, 2016 to 2024). "Mutations in NAGLU and HGSNAT cause the Sanfilippo Syndrome (also called mucopolysaccharidosis Type III) often misdiagnosed with idiopathic developmental delay, attention deficit/hyperactivity disorder and/or ASD." (PMID 28993790, 2017). "Mucopolysaccharidosis type III (MPS III, Sanfilippo disease), is a group of 4 autosomal recessive LSDs caused by pathogenic variants in SGSH, NAGLU, HGSNAT and GNS, respectively." (PMID 35646708, 2022). "HGSNAT-deficient males (MPSIIIC males) showed behavioral alterations that reproduced the observations we and others have previously reported in two other mouse models of Sanfilippo disease, MPSIIIA and MPSIIIB mice." (PMID 27491071, 2016). "The rarest subtypes of mucopolysaccharidosis type III, namely subtype C [OMIM:252930] and D [OMIM:252940], are both hyper-rare AR LSDs with an unknown prevalence, caused by genetic mutations of two different genes: the HGSNAT gene (8p11.2-p11.1) and the GNS gene (12q14.3), respectively." (PMID 37239976, 2023).
mucopolysaccharidosis (5 papers, 2022 to 2025). A group of autosomal recessive or X-linked inherited lysosomal storage disorders affecting the metabolism of mucopolysaccharides, resulting in the accumulation of mucopolysaccharides in the body. "Rare variants in genes causing sphingolipidosis (ARSA (rs201251634) and HGSNAT (rs766835582)) and mucopolysaccharidosis (IDUA (rs532731688, rs74385837) were revealed in SCZ patients but not in controls." (PMID 38248833, 2023). "Similarly, variants in HGSNAT (OMIM 610453) are associated with mucopolysaccharidosis in the vast majority of patients, but isolated retina degeneration has also been described." (PMID 35226187, 2022). "However, it should be noted that a similar situation exists for other genes typically causing LSDs, namely subtypes of NCL and mucopolysaccharidosis: variants in CLN3, MFSD822, 23 and HGSNAT." (PMID 39199020, 2025).
asthma (3 papers, 2015 to 2021). "It was hypothesized that the identified downregulation of M6PR, TPP1, GLB1, NEU1, ACP2, LAMP1 and HGSNAT leads to disorders of lysosome function, which results in asthma by causing T-cell dysfunction." (PMID 25633562, 2015).
retinal disease (3 papers, 2016 to 2020). "Two siblings in one family, while identical for the HGSNAT locus, but discordant for retinal disease, suggest the influence of trans‐acting genetic or environmental modifying factors." (PMID 32770643, 2020). "Furthermore, GRIPT was able to identify three novel retinal disease genes recently published, i.e., POMGNT1 (p = 3.95 × 10−15), TRNT1 (p = 6.25 × 10−8) and HGSNAT (p = 2.10 × 10−7)." (PMID 30477545, 2018). "The genotypes associated with retinal disease identified in this study support the model that the two distinct phenotypes of MPSIIIC and nonsyndromic retinal dystrophy arise due to two nonoverlapping classes of HGSNAT genotype." (PMID 32770643, 2020).
retina degeneration (2 papers, 2020 to 2022). "Firstly, it is by far, the most common HGSNAT allele seen in retinal degeneration patients in this study." (PMID 32770643, 2020).
allergic asthma (1 paper, 2015). A asthma with a basis in a pathological type I hypersensitivity reaction. "The top-ranked DMP (cg03284554) is located upstream of HGSNAT, which has been previously shown to be down-regulated in paediatric allergic asthma." (PMID 26691723, 2015). "Of note, HGSNAT gene expression is down-regulated in paediatric allergic asthma cases compared to controls." (PMID 26691723, 2015).
Anxiety (1 paper, 2016). Intense feelings of nervousness, tension, or panic often arise in response to interpersonal stresses. "HGSNAT-deficient males showed behavioral alterations characterized by anxiety in younger animals and hypoactivity in later stages of the disease." (PMID 27491071, 2016).
atopic asthma (1 paper, 2015). An asthma that is characterized by symptoms that are triggered by an allergic reaction caused by inhaled allergens such as dust mite allergen, pet dander, pollen and mold. "Among the genes identified in the present study (M6PR, TPP1, GLB1, NEU1, ACP2, LAMP1 and HGSNAT) that were significantly associated with lysosomal function, only TPP1 has been confirmed as being associated with atopic asthma." (PMID 25633562, 2015).
breast carcinoma (1 paper, 2024). "The role of LRFN4, BATF2, and HGSNAT in breast cancer remains unexplored." (PMID 39720180, 2024).
ciliopathies (1 paper, 2021). "After extensive analysis of IRD- and ciliopathies-associated genes as well as the complete sequence of HGSNAT, no other candidate variant was identified in these probands." (PMID 34795310, 2021).
cystinosis (1 paper, 2022). Cystinosis is a metabolic disease characterized by an accumulation of cystine inside the lysosomes, causing damage in different organs and tissues, particularly in the kidneys and eyes. "EVs naturally contain lysosomal components including heparan-alpha-glucosaminide N-acetyltransferase (HGSNAT), beta-glucocerebrosidase (GBA), N-acetylgalactosamine-6-sulfate sulfatase (GALNS), cystinosis (CTNS), deficient in MPS III, Gaucher, MPS IVA, and Cystinosin respectively." (PMID 39697359, 2022).
intellectual impairment (1 paper, 2024). "Proband family E-1, whole exome sequencing data analysis identified a bi-allelic pathogenic variant in the HGSNAT gene causing intellectual impairment and ophthalmic, psychiatric, behavioral, and severe neurological manifestations." (PMID 39767643, 2024).
Lysosomal disease (1 paper, 2015). "A previous study demonstrated that loss of HGSNAT activity leads to mucopolysaccharidosis IIIC (MPSIIIC), a lysosomal disease." (PMID 25633562, 2015).
metachromatic leukodystrophy (1 paper, 2023). A rare lysosomal storage disorder characterized by intralysosomal accumulation of sulfatides in various tissues, leading to progressive deterioration of motor and neurocognitive function. "Mutations in IDUA and HGSNAT cause mucopolysaccharidosis I and III types, respectively; mutations in ARSA cause metachromatic leukodystrophy (MLD) that belongs to the sphingolipidosis group." (PMID 38248833, 2023).
Retinal dystrophy (1 paper, 2019). Retinal dystrophy is an abnormality of the retina associated with a hereditary process. "Pericentral retinitis pigmentosa, a specific subtype of retinal dystrophy, has been observed as sole symptom in association with mutations in the HGSNAT gene, encoding the lysosomal enzyme heparin-alpha-glucosaminide N-acetyltransferase a deficiency of which causes MPS IIIC (OMIM #252930)." (PMID 31718697, 2019).
Salmonella Infections (1 paper, 2018). Infections with bacteria of the genus SALMONELLA. "On the other hand, FOXO signaling (TNFSF10, PRKAB1, GADD45B, STK4, STAT3), Salmonella infection (ARPC2, ARPC5L, CCL3L3, CCL4) and lysosome (LAPTM4B, HGSNAT, CD164, ATP6V0A2) pathways were up-regulated, albeit weakly, in the HLA-DR- Teff subset." (PMID 30231065, 2018).
cancer (1 paper, 2022). A tumor composed of atypical neoplastic, often pleomorphic cells that invade other tissues. "No previous research studies were published concerning the relationship between cancer and HGSNAT or ZNF738." (PMID 35910199, 2022).
infection (1 paper, 2023). The state of being infected such as from the introduction of a foreign agent such as serum, vaccine, antigenic substance or organism. "However, BLOC1S1, SCARA3, COL6A1, and HGSNAT were unaffected by HCoV-OC43, suggesting that IRE1α activity is limited to XBP1 splicing during infection." (PMID 37306512, 2023).
neurodevelopmental disorder (1 paper, 2024). A behavioral and cognitive disorder with onset during the developmental period that involves impaired or aberrant development of intellectual, motor, or social functions. "Clinically, he was suspected of having a neurodevelopmental disorder phenotype, while genetically, he was diagnosed as suffering from neurodegenerative disorder caused by a novel, bi-allelic missense variant in HGSNAT gene leading to the identification of Sanfilippo syndrome C disorder." (PMID 39767643, 2024).
retinopathy (1 paper, 2020). "We identify seven novel sequence variants and four previously reported MPSIIIC variants which were in trans with the hypomorphic allele p.(Ala615Thr), thus expanding the phenotypic and genotypic spectrum of HGSNAT‐associated retinopathy." (PMID 32770643, 2020). "Together with the other p.Ala615Thr homozygous patient who also underwent enzyme analysis (NEI‐3), all three showed decreased HGSNAT enzyme activity and urinary GAG/creatinine ratio within the normal range, similar to the other HGSNAT‐associated retinopathy patients in this study." (PMID 32770643, 2020). "The finding that enzyme activities of all three within the normal range, suggested the variants to be benign and the retinopathies were unlikely to be related to HGSNAT." (PMID 32770643, 2020). "Three patients MEH14, MEH15, and MEH16 had a phenotype consistent with HGSNAT‐retinopathy, with slowly progressive degeneration of the midperipheral retina, with two having bi‐allelic HGSNAT variants of unknown significance (MEH16 was not tested for HGSNAT variants)." (PMID 32770643, 2020).
HGSNAT also shares sentences with these, for which no sentence is quoted: attention deficit-hyperactivity disorder (1 paper); cardiovascular diseases (1); Childhood onset (1); epilepsy (1); metabolic disorder (1); MPS III A (1); mucopolysaccharidosis I (1); mucopolysaccharidosis type I (1); Noonan syndrome (1); rheumatoid arthritis (1); sphingolipidosis (1); Splenomegaly (1); Usher syndrome (1).